ATF3 (activating transcription factor 3)
Diseases named in the same sentence as ATF3 in open-access papers (continued):
Sharing a sentence is not in itself a finding about the gene and the disease.
cervical carcinoma (7 papers, 2010 to 2023). A carcinoma arising from either the exocervical squamous epithelium or the endocervical glandular epithelium. "In addition, a previous study has reported that ATF3 competes with E6-associated protein (E6AP) ubiquitin ligase to bind to E6 in cervical cancer cells, thereby acting as a suppressor of the E6 viral protein." (PMID 36522783, 2022). "We can still identify some genes related to cervical cancer progression from the samples of the two patients after treatment, including ATF3, GPX3, IL10, IL6, RAD51AP1, MGMT, WWOX." (PMID 37914994, 2023). "It has been suggested that ATF3, a principal transcriptional factor, is frequently down-regulated in cervical cancer." (PMID 36522783, 2022). "Apparently, ATF3 induces apoptosis and cell arrest through various pathways in cervical cancer cells based on the type of HPV infection involved." (PMID 36522783, 2022). "Activated transcription factor 3 (ATF3) was a stress-induced transcription repressor, it had been shown that ATF3 overexpression enhanced paclitaxel apoptosis in cervical cancer HeLa cells in part by stimulating TAp73, thus, it can act as a tumor suppress factor." (PMID 37914994, 2023). "Our results suggest that ATF3 induction or NF-κB suppression may be useful targets for HPV16-related cervical cancer prevention and treatment." (PMID 36522783, 2022). "Interestingly, ATF3 expression is downregulated in cervical cancer." (PMID 33253291, 2020). "Herein, we have demonstrated that ATF3 acts as a tumor suppressor factor which mediates apoptosis and cell cycle arrest in HPV16-related cervical cancer cells." (PMID 36522783, 2022). "Therefore, it seems that targeting ATF3 as a potential novel intervention through gene therapy or other therapeutic approaches could be a promising strategy to attenuate NF-κB up-regulation in cervical cancer." (PMID 36522783, 2022). "Moreover, for the first time, we have described a novel ATF3-dependent cell cycle arrest induction which impacts on NF-κB expression as one of the most important intracellular transcription factors reported to be constitutively activated in many types of cancers including cervical cancer." (PMID 36522783, 2022). "ATF3 acts as a tumor suppressor factor in HPV16-infected Ca Ski cells and exerts anti-cancer effects on HPV16-related cervical cancer cells potentially by hindering cell growth and inducing cell cycle arrest through the down-regulation of NF-κB." (PMID 36522783, 2022). "Induction of ER-stress in cervical carcinoma cells (HeLa) by glucose deprivation showed early upregulation of ATF4 and other target genes of this stress response pathway such as DDIT3, GADD34, ATF3, and EIF4EBP1 at 24 h." (PMID 33413684, 2021).
endothelial dysfunction (7 papers, 2017 to 2024). In vascular diseases, endothelial dysfunction is a systemic pathological state of the endothelium (the inner lining of blood vessels) and can be broadly defined as an imbalance between vasodilating and vasoconstricting substances produced by (or acting on) the endothelium. "Activating transcription factor 3 (ATF3) is SUMOylation of lysine 42 via SUMO1 and is involved in Ang II-induced endothelial dysfunction." (PMID 35855865, 2022).
esophageal cancer (7 papers, 2018 to 2024). A primary or metastatic malignant neoplasm involving the esophagus. "MLN4924 is a specific inhibitor of Nedd8-activating enzyme that promotes the expression of ATF3 to induce autophagy in esophageal cancer." (PMID 35812340, 2022). "For the first time, we reported that MLN4924, a specific inhibitor of Nedd8-activating enzyme, promoted the expression of ATF3 to induce autophagy in esophageal cancer." (PMID 32398095, 2020). "Next we determined the role of ATF3-mediated autophagy response upon MLN4924 treatment in esophageal cancer cells." (PMID 32398095, 2020). "ATF3 has been reported to affect the degradation of MMP2 at the protein level via the ATF3/MDM2/MMP-2 complex in esophageal cancer cells." (PMID 29966001, 2018). "ATF3 is also one of the immediate-early response genes and is induced by various physiological and pathological stimuli, including anticancer drugs, proteasome inhibitors, growth-stimulating factors like serum, and esophageal cancer cells." (PMID 33332945, 2021). "However, in the present study, we found that inactivation of NF-κB pathway upon MLN4924 treatment acts as a protective role by inducing the ATF3-mediated autophagy in esophageal cancer cells." (PMID 32398095, 2020). "Furthermore, high expression of ATF3 was negatively correlated with the prognostic survival curve in patients with esophageal cancer, suggesting that ATF3 may act as an oncogene in esophageal cancer." (PMID 32398095, 2020). "Pre-treatment of esophageal cancer cells with NAC, a classical ROS scavenger, dramatically attenuated the expression of ATF3 and inhibited the autophagic response induced by MLN4924." (PMID 32398095, 2020). "In addition, microRNA-498 was shown to suppress esophageal cancer through the inhibition of autophagy and M2-like polarization of macrophages via mouse double minute 2 (MDM2)/activating transcription factor 3 (ATF3) signaling pathway." (PMID 36091106, 2022). "In our study, we elucidates a novel mechanism of NF-κB/Catalase/ATF3 pathway in MLN4924-induced protective autophagy in esophageal cancer cells, which provides a sound rationale and molecular basis for combinational anti-ESCC therapy with knockdown ATF3 and neddylation inhibitor (e.g. MLN4924)." (PMID 32398095, 2020). "Since MLN4924 treatment induced the accumulation of ATF4, a member of ATF/CREB subfamily, in esophageal cancer cells, we reasoned whether neddylation inhibition could affect the expression of other members of ATF/CREB subfamily, such as ATF3." (PMID 32398095, 2020). "In esophageal cancer cells, MLN4924 induces the expression of ATF3 by modulating NF-κB-Catalase-ROS pathway to trigger pro-survival autophagy, whereas targeting ATF3 blocks the autophagic response upon neddylation inhibition and thus sensitizes cancer cells to MLN4924-induced apoptosis." (PMID 32398095, 2020). "The ATF3 knockdown completely blocked the conversion of LC3-I to LC3-II upon MLN4924 treatment, indicating a crucial role of ATF3 in MLN4924-induced autophagy in esophageal cancer cells." (PMID 32398095, 2020). "A previous report showed that ATF3 degrades the MMP protein by a proteasome-dependent pathway in esophageal cancer; however, ATF3 was unlikely to regulate the expression of MMP2 and 9 genes or the MMP2 and 9 protein stability in HCT116 cells, in this study." (PMID 29966001, 2018). "However, it is completely unknown whether neddylation inhibition could induce autophagy in esophageal cancer cells and affect the expression of other members of ATF/CREB subfamily, such as ATF3." (PMID 32398095, 2020).
Hyperglycemia (7 papers, 2020 to 2025). An increased concentration of glucose in the blood. "However, the DN, atf3−/−, and clec5a−/− mice exhibited similar hyperglycemia and body weight loss compared with the mice in the citrate and hypoDN groups." (PMID 34172832, 2021). "Animal models of proteinuric and DN (including lipopolysaccharide-treated C57BL/6 mice and db/db mice) have shown upregulation of ATF3 expression in podocytes under stress conditions, such as hyperglycemia and endotoxemia." (PMID 41369384, 2025). "ATF3 can also promote STZ-induced diabetic injury by stabilizing STAT1 expression in hepatic cells, and cardiac-specific HFD-fed ATF3-cKO mice show increased hyperglycemia and glucose intolerance." (PMID 32922364, 2020).
non-small cell lung carcinoma (7 papers, 2011 to 2024). A group of at least three distinct histological types of lung cancer, including non-small cell squamous cell carcinoma, adenocarcinoma, and large cell carcinoma. "Increased ATF3 expression is associated with an increased incidence and invasiveness of non-small cell lung cancer." (PMID 34769496, 2021). "Analogously with this finding, former research indicated that ATF3 accounts for the reinforcing effects on cisplatin cytotoxicity in non-small cell lung carcinoma." (PMID 34098867, 2021). "Additionally, ATF3 is responsible for chemoresistance in non-small cell lung carcinoma and nasopharyngeal cancer." (PMID 34098867, 2021). "Inhibitory effects of 18 towards SUV39H1 were found to provoke endoplasmic reticulum (ER) stress and results in the upregulation of the activating transcription factor 3 (ATF3) and C/EBP homologous protein (CHOP) in non-small cell lung cancers, suggestive of DR5-dependent apoptosis." (PMID 31569621, 2019).
skin cancer (7 papers, 2011 to 2025). "Conversely, ATF3 exhibits high expression levels in breast and skin carcinomas, and can act as an oncogene to participate in carcinogenesis." (PMID 34098867, 2021). "In skin cancer cells, activation of STAT3 by overexpressed ATF3 enhances cell proliferation while ATF3 knockdown abolishes this effect." (PMID 30455690, 2018).
ZIKV infection (7 papers, 2017 to 2024). "More than half of the transcripts upregulated after ZIKV infection in WT cells were also significantly upregulated in ATF3 KO, and these genes were primarily associated with interferon and cytokine signaling." (PMID 39212382, 2024). "We identified the ISR pathway as the upstream signaling cascade leading to ATF3 activation during ZIKV infection with ATF4 as the direct effector of ATF3 in this pathway." (PMID 39212382, 2024). "As expected, during ZIKV infection, ATF3 mRNA and protein were expressed, while in the presence of ISRIB, the levels of ATF3 mRNA decreased, consistent with the effect of ISRIB on ATF4 protein abundance." (PMID 39212382, 2024). "In this study, we show via inhibitor and RNA interference approaches that ZIKV infection initiates the integrated stress response pathway to activate ATF4 which in turn induces ATF3 expression." (PMID 39212382, 2024). "Future transcriptomic studies defining ATF3 genomic occupancy during ZIKV infection will elucidate how this stress-induced transcription factor differentially directs the expression of IFNB1 and other ISGs." (PMID 39212382, 2024). "We show that during ZIKV infection, the integrated stress response pathway stimulates ATF3 which enhances the innate immune response to antagonize ZIKV infection." (PMID 39212382, 2024). "Altogether, these data indicate that ATF3, either directly or indirectly, enhances the expression of antiviral immune response genes during ZIKV infection." (PMID 39212382, 2024). "To better understand the gene regulatory networks controlled by ATF3 that appear to restrict ZIKV infection, we compared changes in the polyA+ transcriptome of A549 WT and ATF3 KO cell lines after 24 hours of mock or ZIKV infection." (PMID 39212382, 2024). "Future studies that establish the direct targets of ATF3, particularly within the IFN pathway and the type of regulation will provide valuable mechanistic insights on the role of ATF3 during ZIKV infection." (PMID 39212382, 2024). "Our data indicate that ATF3 promotes the expression of components within the innate immune response pathway to restrict ZIKV infection." (PMID 39212382, 2024). "To investigate if the ISR pathway was responsible for ATF3 activation during ZIKV infection, we inhibited the ISR pathway in mock- and ZIKV-infected cells using a general ISR inhibitor (ISRIB)." (PMID 39212382, 2024). "Our study reveals crosstalk between the integrated stress response and innate immune response pathways and highlights an important role for ATF3 in establishing an antiviral effect during ZIKV infection." (PMID 39212382, 2024). "Overall, these results show that during ZIKV infection, ATF3 is activated through the ISR pathway and is expected to modulate cellular stress by regulating transcription of specific genes." (PMID 39212382, 2024). "Overall, these data reveal important crosstalk between the integrated stress response pathway, ATF3, and antiviral responses during ZIKV infection." (PMID 39212382, 2024). "We now define the intracellular pathway responsible for ATF3 activation and elucidate the impact of ATF3 expression on ZIKV infection." (PMID 39212382, 2024). "To determine when ATF3 was stimulated during ZIKV infection, we infected cells with ZIKV and examined viral and cellular proteins and RNA levels at different timepoints following infection." (PMID 39212382, 2024). "Research found that ATF3 inhibits ZIKV infection by differentially regulating the transcription of specific innate immune response and autophagy genes." (PMID 38255898, 2024). "Our data reveal the effects of ATF3 regulation within the cell and highlight that ATF3-driven regulation of innate immunity pathways impedes ZIKV infection." (PMID 39212382, 2024). "Given that ATF3 is upregulated in patients during the early acute phase of ZIKV infection, it is likely that ATF3 similarly contributes to the immune response in patients." (PMID 39065267, 2024).
ZIKV infection (continued). "Moreover, in a reanalysis of RNA-seq data collected from peripheral blood mononuclear cells (PBMCs) from patients in early- and late-acute and convalescent stages of ZIKV infection, we determined that ATF3 levels were increased." (PMID 39212382, 2024). "ATF3 acts to limit ZIKV infection by regulating autophagy and, thus, also ZIKV replication." (PMID 38255898, 2024). "ZIKV infection induced substantial changes in the transcriptome in both, WT and ATF3 KO, genotypes." (PMID 39212382, 2024). "Overall, these global gene expression data are consistent with the hypothesis that ATF3 positively regulates the transcription of genes involved in the innate immune response as one mechanism to restrict ZIKV infection." (PMID 39212382, 2024). "One possibility might be that following ISRIB treatment and ZIKV infection, the low levels of ATF3 mRNA are more efficiently translated via the cap-dependent mechanism." (PMID 39212382, 2024). "Finally, we determined that knockout of ATF3 altered the expression of anti-viral innate immune genes during ZIKV infection." (PMID 39212382, 2024). "However, most transcripts had increased expression in both cell types after ZIKV infection with 1,769 transcripts being upregulated in WT and 2,184 transcripts being upregulated in ATF3 KO compared to the mock infection condition." (PMID 39212382, 2024). "While ATF3 is known to be upregulated during ZIKV infection, the mode by which ATF3 is activated, and the specific role of ATF3 during ZIKV infection is unknown." (PMID 39212382, 2024). "Moreover, the induction of ATF3 expression during ZIKV infection is consistent with increased ATF3 levels in two biologically relevant systems to ZIKV infection namely SH-SY5Y neuronal cells and PBMCs isolated from ZIKV-infected patients." (PMID 39212382, 2024). "Thus, we next investigated if ATF4, the master regulator of the ISR pathway, was the upstream activator of ATF3 during ZIKV infection." (PMID 39212382, 2024). "However, the functional significance of ATF3 in ZIKV infection, and whether this stress-induced transcription factor exhibited pro- or anti-viral functions, had not been determined." (PMID 39212382, 2024). "Specifically, the activation of the ISR kinases during ZIKV infection would lead to a shutdown of cap-dependent translation, increase translation of ATF4, and subsequent activation of ATF3." (PMID 39212382, 2024). "In this study, we used ISR-specific inhibitors, and RNA interference (RNAi) approaches to show that during ZIKV infection, the ISR pathway stimulated ATF4 expression which directly activated ATF3." (PMID 39212382, 2024). "Finally, we investigated how ATF3 might enhance the interferon response during ZIKV infection." (PMID 39212382, 2024). "ATF3 binds to the promoter sequences of the autophagy-related genes Beclin-1 and ATG5 and inhibits their expression during ZIKV infection." (PMID 38255898, 2024). "During ZIKV infection, we observed increased levels of ATF4 RNA and protein, and this increase in ATF4 expression led to the activation of ATF3." (PMID 39212382, 2024). "It is therefore possible that differential expression of ubiquitinases and/or deubiquitinases during ZIKV infection and inhibition of the ISR pathway changed ATF3 protein levels." (PMID 39212382, 2024). "Unlike our observation after ZIKV infection, ATF3 in WT cells in response to dsRNA mimic poly I:C negatively affects the expression of IFN response genes." (PMID 39212382, 2024). "ZIKV infection upregulated ATF4 and ATF3 protein and RNA abundance." (PMID 39212382, 2024). "Our data showed that ZIKV infection-induced ATF3 protein expression in WT cells but not in ATF3 KO cells." (PMID 39212382, 2024). "Given these prior studies showing ATF3 regulating the immune response, we reasoned that ATF3 transcriptionally controlled genes involved in the innate immune response promote ISG expression and restrict ZIKV infection." (PMID 39212382, 2024).